TLR6 (toll like receptor 6)
Diseases named in the same sentence as TLR6 in open-access papers (continued):
Sharing a sentence is not in itself a finding about the gene and the disease.
tumor (31 papers, 2010 to 2026). "TLR2 along with TLR1 or TLR6 on tumor-associated microglia mediates an immunosuppressive role by enhancing production of matrix metalloprotease (MMP) to facilitate tumor invasion." (PMID 33520994, 2020). "Studies have shown that tumor-secreted proteoglycans activate the TLR2/TLR6 complex on macrophages, utilizing the body's innate immune system for immune evasion." (PMID 41328346, 2026). "For example, HSP72 and HSP105 on the surface of tumor exosomes can promote tumor metastasis by inducing IL-4 secretion from DCs in a TLR6 and TLR2-dependent manner." (PMID 38633106, 2024). "Metastasis of the LLC also involves the powerful stimulation of tumor-associated macrophages, which produce IL-6 and TNFα by activating TLR-2 and TLR-6." (PMID 38891915, 2024). "Signaling analysis of the tumor-derived versican-mediated TLR2 signaling identified TLR6 as necessary heterodimer and MyD88 as responsible TLR adapter." (PMID 36224342, 2022). "TLR6 mRNA expression was significantly higher in the SCC tumor center (4.48±1.44) than in the tumor margin (0.96±0.48, p<0.05)." (PMID 22808251, 2012). "Moreover, multivariate analysis proved that TLR6 expression status is an independent prognostic factor in every combination with age, sex, pT, pN, pStage, and tumor differentiation." (PMID 37232814, 2023). "Some studies on clinical samples have pointed to TLR6-related tumor progression." (PMID 30388713, 2018). "For instance, activation of TLR2 and TLR6 in macrophages enhances metastasis of tumor cells, wherein receptor activation is mediated by tumor cell-derived versican, an extracellular matrix proteoglycan that is up-regulated in many tumor cells." (PMID 25149452, 2014). "Furthermore, either the TLR2 or TLR6 antibody reduced vitamin D3 signaling and tumor cell progression in vitro." (PMID 23424670, 2013). "Additionally, the 6 markers (KDR, CXCR6, STAT5A, MPL, NFATC3, and TLR6) we found to be downregulated in our late-recurring tumor samples are also biologically relevant to functional T-cell activity, which helps explain their expression and function in this context." (PMID 36195959, 2022). "The CD36/TLR2/TLR6 form a coreceptors complex on DC surface, and the exogenous ligands of tumor‐derived oxLDL and HMGB1‐gDNA complex join the coreceptors complex through binding CD36 and TLR2/TLR6, respectively." (PMID 37786300, 2023). "They find that the Arf1‐ablated tumor cells release OxLDL, HMGB1, and genomic DNA, which together bound to a coreceptor complex of CD36/TLR2/TLR6 on DC surface." (PMID 37786300, 2023). "We found that the Arf1‐ablated tumor cells release oxLDL, HMGB1‐gDNA complex, and also induce expression of CD36, TLR2, and TLR6 in DCs." (PMID 37786300, 2023). "The expression of TLR1, TLR3, TLR5, TLR6, TLR7, TLR8, and TLR10 show significantly decreasing trends from normal tissues to surrounding tumor tissues and to tumor tissues." (PMID 34141706, 2021). "Versican can also activate resident fibroblasts and endothelial cells in tumor stroma through toll-like receptors (TLR) 2 and TLR6, resulting in enhanced neovascularization." (PMID 28035060, 2017). "A recent study has documented that versican can activate tumour-infiltrating myeloid cells through TLR2 and its coreceptors TLR6 and CD14 and elicit the production of proinflammatory cytokines including TNF-α that enhance tumour metastasis." (PMID 20871832, 2010). "Significant prognostic factors affecting 5-year OS with univariate analyses were pN status (N0 vs. N1-3), pStage (Stage IIA-IIIA vs. over IIIB), tumor differentiation (poorly vs. not poorly differentiated), and TLR6 expression status (low vs. high)." (PMID 37232814, 2023). "We found that the Arf1‐ablated tumor cells released HMGB1, oxidized low‐density lipoprotein (oxLDL), and genomic DNA, which might together bind to co‐receptors complex of the CD36/TLR2/TLR6 on the dendritic cell surface." (PMID 37786300, 2023).
tumor (continued). "A recent study has documented that versican, a large extracellular matrix proteoglycan, can activate tumour-infiltrating myeloid cells through TLR-2 and its coreceptors TLR-6 and CD14 and elicit the production of proinflammatory cytokines including TNF-alpha that enhance tumor metastasis." (PMID 20652007, 2010). "We first knocked out Cd36, Tlr2, or Tlr6 in DCs by CRISPR‐Cas9 technique and found that the ASC speck formation was significantly reduced in the Cd36CRISPR‐/−, Tlr2CRISPR‐/− or Tlr6CRISPR‐/− DCs in comparison with that in wild‐type DCs after co‐culture with the Arf1‐ablated tumor cells." (PMID 37786300, 2023). "In our study, TLR family expression, specifically TLR1, TLR3, TLR4, and TLR6, was upregulated in BD3 tumors in comparison with low-grade budding tumors (both in patient and PDX tumors) suggesting the presence of TLR-mediated alterations in the tumor invasive front." (PMID 32719800, 2020). "TLR6 functionally interacts with TLR2 to mediate the cellular response to bacterial lipoproteins and activate the NF-κB pathway and inflammatory events, and consequently, may contribute to tumor development and progression." (PMID 30388713, 2018).
cancer (16 papers, 2009 to 2025). A tumor composed of atypical neoplastic, often pleomorphic cells that invade other tissues. "The change in amino acid from Ser to Pro results in functional deterioration of TLR6 and predisposes individuals to dysregulation of the innate immune system, which can potentially cause development of the cancer." (PMID 30388713, 2018). "Because the exact mechanisms by which TLR6 polymorphisms contribute to cancer pathogenesis are unknown, such elucidation will be a challenge for future research." (PMID 30388713, 2018). "Moreover, TLR6 overexpression is associated with poor outcomes in patients with certain cancers." (PMID 36195959, 2022). "There have been few reports addressing the relationship between TLR6 signaling and cancer progression or prognosis." (PMID 37232814, 2023). "After taking the intersection, we found that TNFAIP6 and TLR6 were not only overexpressed in cancer tissue but also indicated poorer prognosis." (PMID 38204755, 2023). "Inflammation is a key immune-related factor in cancer development and progression, and sequence variation in TLR6 predicts inflammation-related cancer development." (PMID 36195959, 2022). "TLR1, TLR2, TLR3, TLR4, and TLR5 expression levels were high across the six immune subtypes in the pan-cancer data; TLR6, TLR7, TLR8, and TLR10 expression levels were moderate; and TLR9, TLR12P, and TLR8-AS1 expression levels were extremely low." (PMID 35801728, 2022). "In spite of its enhanced expression and activation, the function and role of TLR6 in cancer are still not clearly understood." (PMID 33937394, 2021). "Despite the enhanced expression and activation of TLR6, its function and role in cancer are not clearly understood." (PMID 30388713, 2018). "Expression levels of TLR1 and TLR6 showed decrease in carcinomas as compared with premalignant epithelium." (PMID 27008696, 2016). "The Toll-like receptor 6, (TLR6) is known to activate nuclear factor kappa-B signalling, a candidate therapeutic target in cancer, and activation of the TLR pathway has recently been suggested to have a role in tumourigenesis." (PMID 19357772, 2009). "Additionally, TLR2 and TLR6 expression were found to be poor predictive markers for five distinct forms of cancer, respectively." (PMID 35801728, 2022). "However, they did not observe significant increases in TLR2 expression in the subsequent progression to adenocarcinoma, with TLR1 and TLR6 showing decreased expression levels in carcinomas when compared with premalignant epithelium." (PMID 33922955, 2021). "Similarly, the interaction with TLR4 and TLR6 could indicate a role in the innate immune response, which is often dysregulated in cancer." (PMID 40343258, 2025). "This may reflect a situation in which mouthwashes containing alcohol or other anti-bactericidal agents remove both pathogenic and beneficial oral bacteria, upsetting the balance of TLR6 and TLR4 signaling and potentially increasing the risk of cancer development." (PMID 37232814, 2023). "On the other hand, we recently reported that high expression of TLR6, which recognizes peptidoglycan (PGN) released from gram-positive bacteria in cancer tissue, is predictive of a significantly better prognosis after esophagectomy." (PMID 38376617, 2024). "Additionally, TLR6, TLR7, TLR8, TLR9, and TLR10 expression was up- or down-regulated in different cancer species." (PMID 35801728, 2022). "These outcomes may show that the rs5743810 (Ser249Pro) SNP of the TLR6 gene may be distributed differently among diverse cancer types and ethnicities, and can thus be used as a biomarker for the diagnosis of different cancers (rather than a specific marker for BC)." (PMID 30388713, 2018).
infectious disease (7 papers, 2015 to 2026). A disorder directly resulting from the presence and activity of a microbial, viral, or parasitic agent in humans. "Altogether, these previous findings and ours suggest functional immunophenotypes for TLR1 N248S and TLR6 P249S for infectious diseases." (PMID 31786695, 2020). "Notably, adaptive introgression and local positive selection led to the significantly increased expression of the TLR6, TLR1, and TLR10 genes, which facilitated resistance to infectious diseases but may also be associated with increased hypersensitivity to non-pathogenic allergens." (PMID 30930906, 2019).
bacterial infections (5 papers, 2014 to 2026). "The endometrial epithelial and stromal cell responses to lipopeptides via TLR2, TLR1, and TLR6 provide a mechanism linking a wide range of bacterial infections to inflammation of the endometrium." (PMID 24437488, 2014). "Activation of platelets with thrombin induces an important modulation of TLR1, TLR6, and TLR9 during vascular lesions potentially mediated by bacterial infection." (PMID 31781518, 2019).
adenocarcinoma (2 papers, 2021 to 2023). A common cancer characterized by the presence of malignant glandular cells. "Significant upregulation of TNFAIP6 and TLR6 and downregulation of P2RY13 and CYP27A1 were observed in all three adenocarcinoma cell lines." (PMID 38204755, 2023).
cardiovascular disease (1 paper, 2016). "We confirm our previous finding of the TLR-6 249S variant to be protective regarding cardiovascular diseases." (PMID 26997964, 2016). "We have recently shown that a Toll-like receptor 6 variant (P249S) is associated with susceptibility to cardiovascular disease and speculated that this variant may also be associated with healthy aging in general by decreasing the process of inflamm-aging." (PMID 26997964, 2016).
immune disorders (1 paper, 2023). "Our group found that in the absence of TLR2, MG could induce inflammation via TLR6 in DF-1 cells, or TLR4 could be activated by HMGB1 to trigger MG-induced immune disorders in avian macrophage cells." (PMID 37238096, 2023).
TLR6 also shares sentences with these, for which no sentence is quoted: mastitis (3 papers); ovarian carcinoma (3); Alzheimer disease (2); non-Hodgkin lymphoma (2); ulcerative colitis (2); adult onset asthma (1); allergic rhinitis (1); allergies (1); Arthritis (1); autoimmune thyroid disease (1); B cell lymphomas (1); B-cell chronic lymphocytic leukemia (1); bacterial meningitis (1); cerebral malaria (1); chorioamnionitis (1); chronic obstructive pulmonary disease (1); corneal diseases (1); diffuse astrocytoma (1); diffuse large B-cell lymphoma (1); disseminated candidiasis (1); endometrial cancer (1); eosinophilia (1); esophageal adenocarcinoma (1); esophageal cancer (1); Gastric Metaplasia (1); gastritis (1); gram-positive bacterial infections (1); Graves disease (1); heart transplant (1); inflammation (1).
A further 19 diseases each share a sentence with TLR6 in 1 paper.